SRC (SRC proto-oncogene, non-receptor tyrosine kinase)
Diseases named in the same sentence as SRC in open-access papers (continued):
Sharing a sentence is not in itself a finding about the gene and the disease.
colon carcinoma (continued). "Indeed, several research groups have reported the importance of Chr20 amplification in colon cancer, and attributed such effect to the location of multiple oncogenes such as BCL2L1, AURKA, TPX2, and SRC on this chromosome." (PMID 38593144, 2024). "Dual inhibition of SRC and MET led to synergistic cytotoxic effects in HNSCC models, and this combination targeting has also emerged as a promising therapeutic strategy for colon cancer." (PMID 31731442, 2019). "Next, the expression of phosphorylated and total MET and SRC was evaluated by Western blotting; the variable expression of these proteins did not correlate with cetuximab response in colon cancer cells." (PMID 24714091, 2014). "Prior study also proposed that both enhanced SRC activity and EGFR phosphorylation at Y845 could be a potential mechanism of cetuximab resistance in colon cancer." (PMID 25301722, 2014). "In addition, FGFR4-signaling activated the oncogenic SRC, ERK1/2 and AKT pathways in colon cancer cells and promoted an increase in cell survival." (PMID 23696849, 2013). "In addition, SRC is elevated in the premalignant tissues in CRC, which could result in induction of apparent loosening of the clusters of colon cancer cells." (PMID 29740162, 2018).
colorectal cancer (69 papers, 2001 to 2025). A primary or metastatic malignant neoplasm that affects the colon or rectum. "SRC is associated with thrombocytopenia and colorectal cancer, and the gene product c-SRC, derived from the SRC gene, is overexpressed and highly activated in various human tumor cells." (PMID 37373516, 2023). "PTPRC is also related to tumor necrosis and disrupts normal T- and B-cell signaling through SRC kinase pathways—which are separately implicated in colorectal cancer through amplification." (PMID 31356589, 2019). "Based on these findings, it can be hypothesized that SRC may increase susceptibility to colorectal cancer." (PMID 40559953, 2025). "Leveraging pathway information can enhance the concordance of shRNA and CRISPR screens and provide clinically relevant findings such as the potential efficacy of dasatinib, an inhibitor of SRC, for colorectal cancer patients with mutations in the WNT signaling pathway." (PMID 37863651, 2024). "Similarly, BRAF V600E mutation and SRC mutations have been found to be mutually exclusive in colorectal cancer patients, and both could serve as molecular markers for prognosis." (PMID 34507532, 2021). "For example, network pharmacology prediction and molecular docking of active ingredients in Salvia miltiorrhiza have been performed, and SRC, IL6, and INS were found to be associated with colorectal cancer." (PMID 39689118, 2024). "Although the role of SRC in chemoresistance in tumors such as breast, lung, and colorectal cancers has been extensively studied, its role in endometrial cancer remains relatively unexplored." (PMID 39664567, 2024). "piR-54265 interacts with PIWI2 to form the PIWI2/STAT3/p-SRC complex and promotes the malignant phenotype of colorectal cancer cells by increasing STAT3 phosphorylation." (PMID 38182573, 2024). "SRC was a prognostic factor for overall survival in patients with colorectal cancer and glioblastoma multiforme." (PMID 35121801, 2022). "A detailed explanation how miR-181a promotes the SRC/VEGF signaling pathway was shown in preclinical models of colorectal cancer." (PMID 32571344, 2020). "Correlation between EGFR, AKT1, MYC, KRAS and SRC and, colorectal cancers separately or in combination with the other genes are studied and confirmed." (PMID 29511483, 2017). "This suggests that the SRC-PRKCD cascade is a novel therapeutic target in Cetuximab-resistant colorectal cancer, and construction of phosphorylation network using phosphoproteomic data will contribute to screening novel kinases as drug targets." (PMID 28874695, 2017). "Taken together, these results indicate that PTPRO controls of the MAPK signaling pathway in colorectal cancer cells by regulating SRC activity." (PMID 25301722, 2014). "In contrast to our findings, SNX10 was reported to have a tumor suppressive effect in mouse inflammation-driven colorectal cancer models, with knockout leading to increased chaperone-mediated autophagy and mTOR activation and reduced autophagic degradation of SRC." (PMID 36795488, 2023). "Thus, these compounds, especially SRC inhibitors, appear to be promising drugs for overcoming cetuximab resistance in colorectal cancer." (PMID 28874695, 2017). "The FGF-2-FGFRs-SRC-αvβ5 integrin loop might be explored as candidate therapeutic target to block colorectal cancer invasion." (PMID 25973543, 2015). "Furthermore, microRNA-23b and miRNA-145, which are downregulated in many prostate and colorectal cancers, repress SRC and YES activity." (PMID 26087188, 2015). "Notably, suppression of EGFR, SRC, STAT3, and AKT1, which are implicated in both inflammation and carcinogenesis, opens avenues for investigating BRLE in chemoprevention of colitis-associated colorectal cancer." (PMID 41465478, 2025).
colorectal cancer (continued). "Meanwhile, excessive activation of c-MET, EPHA2 and other RTKs is required for maintaining maximal SRC activity in colorectal cancer cells, suggesting that SFK deregulation may create a feedback loop whereby SFK activity increases with RTK activity to fuel tumor promotion." (PMID 26087188, 2015). "Research has demonstrated that curcumin effectively alleviates gingival overgrowth by inhibiting the phosphorylations of SRC and JNK, and it also enhances the therapeutic effects of chemotherapy against colorectal cancer cells." (PMID 39329977, 2024). "In colorectal cancer, PIWIL2 has been shown to interact with STAT3 and phospho-SRC leading to STAT3 phosphorylation and an increase in the proliferation, metastasis and chemoresistance of colorectal cancer cells." (PMID 38303021, 2024). "Notably, SRC’s significant involvement in colorectal carcinoma (CRC) pathogenesis is underscored by higher expression levels observed in CRC patient samples compared with normal mucosa." (PMID 39234565, 2024). "The protein kinases RAF and SRC are validated therapeutic targets in KRAS-mutant pancreatic ductal adenocarcinomas, colorectal cancers and non-small-cell lung cancers and we show that both must be inhibited to block growth of these cancers." (PMID 33130216, 2021). "Since SRC and EGFR appear to cooperate to increase tumorigenicity, dual inhibition of SRC and EGFR has been proposed, such as in head and neck squamous cell carcinoma and colorectal cancer." (PMID 28513565, 2017). "In colorectal cancer, overexpression of ELF4 transactivates fibroblast growth factor receptor 4 (FGFR4) and non-receptor tyrosine kinase (SRC) to facilitate the metastasis of colorectal cancer." (PMID 40083328, 2025). "When poorly metastatic colorectal cancer cells were stably transfected with AIP, there was increased activation of SRC, JNK, and AKT kinases and characteristics of the more metastatic, invasive colorectal cancer cell line, KM12SM, including increased migration, EMT, adhesion, and invasion." (PMID 38479600, 2024). "PGE2 promotes colorectal cancer cell invasion via PI3K 71 and EGFR transactivation by SRC." (PMID 36110531, 2022). "For example, piRNA‐54265 can bind to the PIWIL2 protein and promote the formation of the PIWIL2/STAT3/phosphorylated SRC (p‐SRC) complex, activating STAT3 signalling and promoting the proliferation, metastasis and chemotherapy resistance of colorectal cancer cells." (PMID 33942984, 2021). "For instance, piRNA-54265 binds with the PIWIL2 protein and promotes the formation of the PIWIL2/STAT3/phosphorylated-SRC (p-SRC) complex, which activates STAT3 signaling and promotes the proliferation, metastasis, and chemo-resistance of colorectal cancer cells." (PMID 33802524, 2021). "Dasatinib plus FOLFOX with or without cetuximab in metastatic CRC failed to inhibit SRC, which indicates meaningless clinical activity in refractory colorectal cancer." (PMID 33193697, 2020). "Likewise, treatment of pancreatic cancer cells with tyrosine phosphatase inhibitors increased pYA of SRC in adherent cells, while PTPL1 inactivation in colorectal cancer cells promoted anchorage-independent cell growth." (PMID 26087188, 2015). "Our results demonstrate that SRC Gln531AMB plays no role in the development or in the progression of colorectal cancer among Italian patients." (PMID 11161376, 2001). "Furthermore, we performed a detailed assessment of potential SL interactions in colorectal cancer (CRC) and demonstrated that SRC, along with its inhibitor dasatinib, could serve as a potential SL partner for mutations in the WNT signaling pathway." (PMID 37863651, 2024). "Therefore, inhibition of SRC activity and/or activation of CDK1 could sensitize human colorectal cancer cells to VU‐0365114." (PMID 37842807, 2024). "In the specific context of colorectal cancer, we observed reduced phosphorylation of EGFR and MET following lovastatin treatment, but no significant changes in SRC phosphorylation." (PMID 40832614, 2025).
pancreatic cancer (65 papers, 2002 to 2026). "Recently, FBXL7 promoter hypermethylation was associated with its downregulation, c-SRC induction and tumor progression in prostate and pancreatic cancers." (PMID 35887149, 2022). "Mechanistically, the occurrence of DNV was traceable to the activated SRC gene, and it was suggested that homotypic cell cannibalism, regulated by the nuclear protein 1, opposed metastasis in pancreatic cancer." (PMID 38341593, 2024). "Indirubin derivative (IRD) E738, NS-018 and SKLB-850, dual JAK2/SRC inhibitors, have demonstrated inhibitory effects in pancreatic cancer, multiple myeloma and B-cell lymphoma." (PMID 37147297, 2023). "Some authors debrided DPYSL3 as a metastasis suppressor, while others reported it facilitates pancreatic cancer cell dissemination via a strong interaction with other cell adhesion factors, including Ezrin, focal adhesion kinase and c-SRC." (PMID 36870971, 2023). "The F-box and leucine-rich repeat protein 7 (FBXL7) is a potential tumor-suppressing gene, one that is frequently hypermethylated in pancreatic cancer and where the encoded protein promotes the degradation of AURKA, BIRC5 and c-SRC." (PMID 35887149, 2022). "Recently, FBXL7 promoter hypermethylation was associated with the FBXL7 silencing and overexpression of its target protein, c-SRC, increasing metastasis promotion in prostate and pancreatic cancers." (PMID 35887149, 2022). "SRC is a member of the SRC family kinases (SFK) with pleotropic roles in the growth, survival, and invasion of pancreatic cancer and suppression of SRC activity by dasatinib slows the growth of PDAC models in vitro and in vivo." (PMID 31735913, 2020). "PDGFR/SRC signaling is a therapeutic target in pancreatic cancer with reports of SRC also potentiating PDGFRA activity in other cancer models." (PMID 33213062, 2020). "Western blotting showed that activated SRC (Y416) was a feature among a panel of patient-derived pancreatic cancer cell lines." (PMID 31735913, 2020). "Collectively, ASPH activated the SRC signaling pathway to generate and maintain malignant phenotypes in pancreatic cancer." (PMID 31888763, 2019). "ADAM12 or ADAM15 interacts with SH3 domain of SRC, resulting in activation of the SRC cascade in pancreatic cancer cells." (PMID 31888763, 2019). "Compared to a negative-low level, a moderate-very high level of ASPH, ADAM12, activated SRC, and MMPs correlated with curtailed overall survival (OS) of pancreatic cancer patients (log-rank test, ps < 0.001)." (PMID 31888763, 2019). "SRC proteins binding to the cytoplasmic part of RTKs have been shown to be activated in lung, breast and pancreatic carcinoma cells." (PMID 29856777, 2018). "Since SRC is a suitable target in chemotherapy, its overexpression in pancreatic cancer refers to the crucial role of SRC in patients." (PMID 29511477, 2017). "Many studies have indicated that the EGFR/AKT/p21 and EGFR/SRC/E-cadherin pathways play key roles in the proliferation, cell cycle control, migration and invasion of pancreatic cancer cells." (PMID 25635996, 2015). "Consistent with this, concomitant targeting of EGF-R, TGF-β and SRC has been suggested as a novel therapeutic approach in pancreatic cancer." (PMID 26588899, 2015). "Similarly, synergy was found between FTY720 and the RTK/SRC/TEC inhibitor dasatinib in inhibiting pancreatic cancer proliferation." (PMID 35454859, 2022). "Co-targeting STAT3 and EGFR or STAT3 and SRC suppressed cell growth in pancreatic cancer." (PMID 35600368, 2022). "Inhibition of SRC signaling may retard pancreatic tumor growth and enhance gemcitabine cytotoxicity in xenografts of pancreatic cancer in mouse models." (PMID 34314382, 2021). "ASPH promotes pancreatic cancer progression through activating the SRC signaling pathway." (PMID 31888763, 2019). "We hypothesized ASPH acts as an activator of SRC signaling to promote tumor progression in pancreatic cancer." (PMID 31888763, 2019).
pancreatic cancer (continued). "Hence, our systematic analysis not only proposed amplification of ADAM9 which could be utilized as a biomarker for PDAC metastasis, but also offered support for the utilization of SRC inhibitor (Bosutinib) in the treatment of pancreatic cancer." (PMID 36434634, 2022). "Thus, we speculated that the ectopic activation of the EGFR/AKT/p21 and EGFR/SRC/E-cadherin pathways might partially account for the effects of miR-1178 in pancreatic cancer cells." (PMID 25635996, 2015). "Compound 17 (quercetin-3-methyl ether) interacted with multiple key targets related to pancreatic cancer, including AKT1, EGFR, TNF, CASP3, and SRC, and occupies a central position within the PPI network, indicating the potential regulatory interaction." (PMID 41006588, 2025). "Integrin α5β1 promotes cetuximab resistance in head and neck cancer; the overexpression of the integrin β1 subunit induces SRC and AKT signalling and promotes cetuximab resistance in pancreatic cancer." (PMID 39063187, 2024). "ASPH activates SRC cascade in the primary PDAC tumor, upregulates downstream target genes (e.g., MMPs), and contributes to multiple steps of pancreatic cancer metastasis." (PMID 31888763, 2019). "MMPs act as outlets of SRC cascade and direct executors for ECM degradation/remodeling to facilitate invasion and metastasis of pancreatic cancer cells." (PMID 31888763, 2019). "In vivo, PEAK1-dependent kindles induced by oncogenic KRas amplify the loop between SRC, PEAK1, and ERBB2 drive pancreatic cancer." (PMID 28871116, 2017). "In pancreatic cancer, overexpressed EGFR regulates downstream signaling activation, including PKC, PI3K/AKT/mTOR, SRC, STAT and RAS/RAF/MEK1/ERK1/2, and regulate numerous EGFR-interacting proteins." (PMID 27399694, 2016). "More recently, concomitant targeting of SRC, EGF-R, and transforming growth factor (TGF)-β has been suggested as a novel therapeutic approach in pancreatic cancer." (PMID 26588899, 2015). "Notably, in pancreatic cancer, gemcitabine efficacy necessitates p38-MAPK activation, while gemcitabine resistance is augmented by the activation of STAT5, SRC, and STAT3." (PMID 39000545, 2024). "Moreover, LOXL2 promotes the activation of FAK/SRC and is involved in regulation of expression of CDH1, Snail, and L1CAM, all of which are related to EMT and invasiveness of pancreatic tumor cells." (PMID 38560567, 2024). "Additionally, the usefulness of a three-gene signature (PRKN, SRC and VDAC1) was evaluated based on genes related to mitophagy to predict survival in pancreatic cancer patients." (PMID 38048216, 2023). "Finally, aberrantly activation of SRC occurs in approximately 70% of PDAC patients and contributes to tumorigenesis and progression of pancreatic cancer." (PMID 36324587, 2022). "The activation of c-SRC (SRC) induces EMT, leading to the development of pancreatic cancer." (PMID 35903358, 2022). "Although KRAS activation was linked to SRC overexpression in pancreatic carcinoma, the same study failed to establish a link between mt KRAS and SRC overexpression." (PMID 35877239, 2022). "Notably, both SHC1-engaged SRC and gp130-activated JAK2 signals increased the phosphorylation of STAT3 [Y705], a critical step in pancreatic cancer progression." (PMID 34921158, 2021). "SRC, a 60-kDa member of the non-receptor tyrosine kinase family, is upregulated in 70% of pancreatic tumors." (PMID 34314382, 2021). "Moreover, LOXL2 contributes positively to the activation of FAK/SRC and influences the expressions of CDH1, Snail and L1CAM, which are all related to EMT and the invasiveness of pancreatic tumor cells." (PMID 27285767, 2016). "The presence of the CD133/ERK/SRC signaling axis indicates that CD133 acts as a characteristic mesenchymal regulator and is a “functional” marker of migration, invasion, and metastasis in pancreatic cancer." (PMID 24468059, 2014).
pancreatic cancer (continued). "Taken together, targeting of SRC activity by dasatinib or siRNA enhanced gemcitabine-induced cell death by inducting apoptotic cell death and reducing the level of ALDH1A1 expression in ALDH1A1-enriched pancreatic cancer MIA PaCa-2 cells." (PMID 24676703, 2014). "Collectively, these findings identify SRC as a direct target of OA and demonstrate that OA suppresses PDAC progression through the inhibition of the SRC/PI3K/AKT signaling pathway, thereby supporting its potential as a safe and effective therapeutic candidate for pancreatic cancer." (PMID 42194035, 2026). "In spite of the genomic heterogeneity observed in PDAC, the nonreceptor tyrosine kinase SRC is present at high levels in most PDAC specimens and pancreatic cancer cell lines." (PMID 31735913, 2020).